ORAI1 (ORAI calcium release-activated calcium modulator 1)
Diseases named in the same sentence as ORAI1 in open-access papers (continued):
Sharing a sentence is not in itself a finding about the gene and the disease.
acute kidney injury (4 papers, 2021 to 2025). Sudden and sustained deterioration of the kidney function characterized by decreased glomerular filtration rate, increased serum creatinine or oliguria. "Orai1 promotes lymphocyte IL17 expression in CD4+ cells and, in turn, contributes to acute kidney injury (AKI) and AKI-to-CKD progression." (PMID 34764278, 2021).
allergic disease (4 papers, 2012 to 2025). An immune response that occurs following re-exposure to an innocuous antigen, and that requires the presence of existing antibodies against that antigen. "This is the first report to state the relationship between the genetic polymorphisms of ORAI1 and allergic diseases." (PMID 22253717, 2012). "Given the polygenic nature of allergic diseases such as AD, the susceptibility gene ORAI1 could provide a new clue in the pathogenesis of AD." (PMID 22253717, 2012). "In human ORAI1 knock-in mice, DS-2741a inhibited T cell activation and MCs degranulation, and alleviated house dust mite–induced dermatitis, supporting the therapeutic potential of ORAI1 blockade in allergic diseases." (PMID 41235218, 2025).
Anhidrotic ectodermal dysplasia (4 papers, 2017 to 2025). "Patients also had non‐immunological symptoms including congenital muscular hypotonia and anhidrotic ectodermal dysplasia, which are typical of CRAC channelopathy due to LOF mutations in STIM1 and ORAI1." (PMID 32609955, 2020).
diffuse large B-cell lymphoma (4 papers, 2018 to 2022). "Latour el al have demonstrated that Orai1 and Stim1 could regulate diffuse large B cell lymphoma (DLBCL) cell motility and dissemination, promoting homing of tumor B cells to extra-nodal sites." (PMID 34579758, 2021). "Inhibition of the SOCE by Orai1 down-expression or classical inhibitors enhance the RTX-induced apoptosis on Follicular Lymphoma and Diffuse Large B Cell lymphoma cell lines." (PMID 31320998, 2019).
Hyperglycemia (4 papers, 2017 to 2025). An increased concentration of glucose in the blood. "Hyperglycemia induces SOCE via Orai1, activating calpain, which causes F-actin disorganization and nephrin loss, leading to podocyte injury." (PMID 41009556, 2025). "Hyperglycemia causes calcium overload by activating the ORAI calcium release-activated calcium modulator 1 (ORAI1) channel-mediated Ca2+ internal flow pathway." (PMID 34616789, 2021). "In summary, hyperglycemia increased Orai1, CnA, and p-ERK1/2 protein levels and fission protein Drp1 activity, but decreased fusion protein levels in the hearts of ZDF rats." (PMID 33637715, 2021). "Hyperglycemia or blockade of insulin signaling reduces the expression of ORAI1-3." (PMID 29203863, 2017).
liver cancer (4 papers, 2020 to 2025). An epithelial or non-epithelial malignant neoplasm that arises from the liver. "Briefly, this study provides phylogenetic evidence for a possible HBV-driven epigenetic remodeling that alters the expression pattern of Ca2+ homeostasis-associated genes in STIM1- or Orai1 overexpressing liver cancer stem-like cells for a possible mutual survival outcome." (PMID 36556285, 2022). "Inhibition of Orai1-mediated Ca2+ influx, known as store-operated Ca2+ entry (SOCE), significantly enhances the sensitivity of the human liver cancer cell line HepG2 to 5-FU." (PMID 39744692, 2025).
muscular dystrophy (4 papers, 2012 to 2022). Muscular dystrophy (MD) refers to a group of more than 30 genetic diseases characterized by progressive weakness and degeneration of the skeletal muscles that control movement. "Overall, these results extend prior findings by demonstrating that postdevelopmental functional Orai1 deficiency reduces the severity of muscular dystrophy in mdx mice through normalization of both Ca2+ homeostasis and sarcolemmal integrity." (PMID 35939054, 2022). "In this study, we systematically studied the contribution of Orai1-mediated Ca2+ entry in the progression of muscular dystrophy by applying a shRNA targeting Orai1 and systematic inhibition of SOCE using BTP2." (PMID 23185465, 2012). "Consistent with the idea that dysregulated activation of STIM1/Orai1-dependent SOCE promotes Ca2+-mediated muscle fiber degeneration in muscular dystrophy, STIM1 and Orai1 expression levels and SOCE activity were reported to be increased in dystrophin-deficient mdx mice." (PMID 35939054, 2022).
psoriasis (4 papers, 2021 to 2025). An autoimmune condition characterized by red, well-delineated plaques with silvery scales that are usually on the extensor surfaces and scalp. "Results and discussion: Store operated calcium (Ca2+) entry (SOCE), mediated by STIM1 and Orai1, is crucial for the function of keratinocytes and immune cells, the two major players in psoriasis." (PMID 36817139, 2023).
rheumatoid arthritis (4 papers, 2013 to 2019). A chronic, systemic autoimmune disorder characterized by inflammation in the synovial membranes and articular surfaces. "We further utilized this antibody to characterize Orai1 expression on immune cell subsets from blood and rheumatoid arthritis synovial fluid." (PMID 24376610, 2013).
Arterial thrombosis (3 papers, 2022 to 2023). The formation of a blood clot inside an artery. "Orai1 proteins have been implicated in platelet’s SOCE and in regulation of arterial thrombosis." (PMID 36291093, 2022). "Since STIM1/Orai1-mediated SOCE in platelets is sufficient for thrombus formation without affecting hemostasis, it is a promising target for the treatment of thrombo-occlusive disorders including arterial thrombosis, myocardial infarction and ischemic stroke." (PMID 35203269, 2022).
B cell lymphoma (3 papers, 2013 to 2022). "In accord, STIM1- and Orai1-deficient subjects displayed a significant propensity to develop human herpesvirus-8-dependent Kaposi sarcoma and Epstein–Barr virus-associated B-cell lymphoma." (PMID 35884372, 2022). "In several cases, chronic viral infections in ORAI1- and STIM1-deficient patients have caused Epstein–Barr virus (EBV)-positive B cell lymphoma and Human herpesvirus (HHV) 8-associated Kaposi sarcoma, suggesting that SOCE may be required for antitumour immunity by CD8+ T cells." (PMID 23922331, 2013). "Impaired antitumour immunity and CTL function in Stim1fl/flStim2fl/flCd4Cre mice likely explain why human patients lacking SOCE due to mutations in the CRAC channel genes ORAI1 and STIM1 develop virus-associated malignancies such as EBV+ B cell lymphoma and HHV8+ Kaposi sarcoma." (PMID 23922331, 2013).
depression (3 papers, 2023 to 2025). "Several mechanisms may underlie the mitigation of LPS-induced behavioral depression in male Orai1 cKO mice." (PMID 37679321, 2023). "In the Hp, loss of Orai1 attenuates inhibitory neurotransmission and inflammation-induced astrocyte Ca2+ signaling, while in Orai1 knockout mice amelioration of LPS-induced depression-like behaviors including anhedonia and helplessness were reported." (PMID 39528842, 2025). "In line with these cellular changes, Orai1 knockout mice showed amelioration of LPS-evoked depression-like behaviors including anhedonia and helplessness." (PMID 37679321, 2023). "A final point is that it is unclear to what extent the astrocyte Orai1-regulation of inflammation and depression is similar between male and female mice." (PMID 37679321, 2023). "In this study, we assessed the role of the calcium channel, Orai1, for astrocyte reactivity and inflammation-evoked depression behaviors in mice." (PMID 37679321, 2023). "Therefore, we used these tests to address the role of Orai1 channels in mediating LPS-evoked depression behaviors in mice." (PMID 37679321, 2023). "Moreover, abrogation of Orai1 function mitigates inflammation in the hippocampus in vivo and protects mice against depression-like phenotypes following induction of global inflammation." (PMID 37679321, 2023). "Thus, a multitude of effects may contribute to reduced GABAergic tone in the Orai1 cKO mice to relieve depression-like behaviors." (PMID 37679321, 2023). "Taken together, these results show that astrocyte Orai1 signaling regulates multiple interlinked cellular processes that impact neuroinflammation in mice, identifying astrocyte Orai1 as potential target for modulation of inflammation-evoked brain inflammation and depression." (PMID 37679321, 2023). "We postulate that the strong suppression of sIPSCs in astrocyte Orai1 cKO mice may relieve depression-like behaviors through a similar effect, raising the possibility that therapeutically targeting astrocytic Orai1 channels may offer a path for mitigating depression." (PMID 37679321, 2023). "Thus, deletion of astrocyte Orai1 confers relatively specific protection against behavioral depression without causing global impairments in locomotion, anxiety, exploratory behavior, or cognition, and moreover, reaffirm that the LPS-evoked depression is not simply a reflection of sickness behavior." (PMID 37679321, 2023).
diabetic nephropathy (3 papers, 2017 to 2022). "The cycling of ion channel complexes through clathrin-coated vesicles has important implications in the pathophysiology of diabetic kidney disease and may also be related to the disease processes of ORAI1/STIM1 mutations." (PMID 29203863, 2017). "Our results suggest that tightly balanced insulin action targeting podocyte Orai1 is critical for maintaining filter integrity, which provides novel perspectives on therapeutic strategies for proteinuric diseases, including diabetic nephropathy." (PMID 34764278, 2021). "Taken together, our results provide a novel perspective on growth factor signaling by demonstrating the involvement of Orai1 in the pathogenesis of podocyte dysfunction and suggest new possible therapeutic strategies for proteinuric kidney diseases such as diabetic nephropathy." (PMID 34764278, 2021).
dilated cardiomyopathy (3 papers, 2020 to 2022). Cardiomyopathy which is characterized by dilation and contractile dysfunction of the left and right ventricles. "This suggests that the loss of Orai1 accelerates the pathology and results in the more raid development of dilated cardiomyopathy and HF." (PMID 36291148, 2022). "The loss of Orai1 thus accelerated the development of dilated cardiomyopathy and HF." (PMID 33117812, 2020). "Similarly, heart-specific suppression of Orai1 in larvae and adult drosophila resulted in reduced contractility that is consistent with dilated cardiomyopathy." (PMID 36291148, 2022). "In addition, inducible RNAi to specifically suppress Orai1 expression in the Drosophila heart resulted in significant delays in post-embryonic development, premature death in adults, and impaired cardiac function due to myofibril disorganization consistent with dilated cardiomyopathy." (PMID 33117812, 2020).
endothelial dysfunction (3 papers, 2022 to 2025). In vascular diseases, endothelial dysfunction is a systemic pathological state of the endothelium (the inner lining of blood vessels) and can be broadly defined as an imbalance between vasodilating and vasoconstricting substances produced by (or acting on) the endothelium. "In addition, the plasmatic concentration of Orai1 was positively associated with age-related markers of endothelial dysfunction and inflammation." (PMID 36429103, 2022). "Furthermore, Orai1 was positively associated with markers of inflammation and endothelial dysfunction that are closely related to age." (PMID 36429103, 2022). "We found that Orai1 knockdown in PAH-hPECs induces increased BMPR2 expression, suggesting that Orai1 inhibition should partly reduce endothelial dysfunction that occurs in PAH by restoring BMPR2 expression." (PMID 41212057, 2025). "Concentrations of Orai1 in donors’ plasma were related to endothelial dysfunction, as suggested by the positive and significant correlation of these concentrations with ADMA levels." (PMID 36429103, 2022). "Orai1 is likely a key mediator in PTH-induced endothelial dysfunction in CVD." (PMID 35369318, 2022). "Circulating levels of Orai1 were correlated with the inflammatory factor TNF-α and with the endothelial dysfunction marker asymmetric dimethylarginine." (PMID 36429103, 2022). "For example, Orai1 and STIM1 mediate histamine-induced endothelial inflammation, and Orai1 is involved in endoplasmic reticulum stress–induced endothelial dysfunction." (PMID 35369318, 2022). "Our results suggest that Orai1 and the downstream calmodulin/calcineurin/NFATC1/COL1A1 signaling pathway may play an important role in PTH-induced endothelial dysfunction and may be key potential therapeutic targets for preventing or treating SHPT-induced CVD." (PMID 35369318, 2022).
Hypocalcemia (3 papers, 2023 to 2026). An abnormally decreased calcium concentration in the blood. "Increased concentrations of 5-HT induce increased expression levels of the main Ca transporters (ORAI1 and PMCA2), increasing their excretion in milk and causing transient hypocalcemia." (PMID 38067022, 2023).
ischemic stroke (3 papers, 2020 to 2023). A stroke disorder caused by obstruction of blood flow to the brain, due to thrombotic (local blood clot formation) or embolic (due to a blood clot or other material traveling from another site) event. "Accordingly, Orai1-deficiency results in a minimized infarct volume and an improved clinical outcome after induction of the tMCAO ischemic stroke mouse model without any sign of intracranial hemorrhagic bleeding." (PMID 35203269, 2022). "Lack of functional Orai1 in mice reduced GPVI-dependent PS exposure and protected against tissue damage during ischemic stroke without increasing the risk of intracerebral hemorrhage." (PMID 37108326, 2023). "Although both Orai1 and Orai2 contribute to SOCE, they play distinct roles in ischemic stroke." (PMID 33328896, 2020). "Although 2-APB protects from severe ischemic stroke in a mouse model of tMCAO and was described to interfere with the STIM1/Orai1 coupling, the underlying mechanism is not well-defined and most likely includes additional processes that are independent of SOCE signaling in platelets." (PMID 35203269, 2022).
lymphoma (3 papers, 2020 to 2024). A malignant (clonal) proliferation of B- lymphocytes or T- lymphocytes which involves the lymph nodes, bone marrow and/or extranodal sites. "The Orai1 inhibitor RP4010 showed therapeutic promise in preclinical work, but a clinical trial in patients with refractory or relapsed lymphoma (NCT03119467) has been terminated because of safety concerns." (PMID 32575848, 2020).
Obesity (3 papers, 2017 to 2022). Accumulation of substantial excess body fat. "We did not detect differences in expression of Orai1 in the livers of mice with genetic or high-fat diet (HFD)-induced obesity." (PMID 29243589, 2017). "In order to determine the impact of obesity on SOCE in the liver, we isolated primary hepatocytes from lean wild-type (WT) and genetically obese (Lepob/ob) mice and measured Ca2+ influx through STIM/Orai1 using the ratiometric calcium dye, Fura-2AM." (PMID 29243589, 2017).
pancreatic adenocarcinoma (3 papers, 2019 to 2023). "ORAI1 and STIM1 are anti-apoptotic in pancreatic adenocarcinoma cell lines and siRNA-mediated depletion of ORAI1 and STIM1 increased apoptosis induced by 5-fluorouracil (5-FU) or gemcitabine." (PMID 30917547, 2019). "In pancreatic adenocarcinoma, both Stim1 and Orai1 mediate SOCE and have a pro-survival anti-apoptotic role, as Orai1 and/or Stim1 silencing by siRNA enhance 5-Fluoro-Uracile (5-FU) and gemcitabine induced apoptosis." (PMID 30884858, 2019).
Primary immunodeficiencies (3 papers, 2016 to 2021). "Because the patient’s symptoms were consistent with primary immunodeficiency (PID), genomic DNA sequencing with a PID gene panel was performed (Invitae) and revealed a homozygous variant of uncertain significance (VUS) in the ORAI1 gene." (PMID 33650027, 2021).
Sepsis (3 papers, 2022 to 2024). Sepsis is defined as life-threatening organ dysfunction caused by a dysregulated host response to infection. "Nevertheless, the evidence that the small molecule inhibitor BTP2, which is commonly employed to inhibit Orai1, halts sepsis- and ventilation-induced ALI suggests that Orai1 can somehow interact with TRPC1 and TRPC4 also in mice pulmonary endothelial cells." (PMID 36834672, 2023). "Aberrant STIM1 and Orai1 glycosylation have been reported in a number of disorders, for instance, it has been detected in myopathies with tubular aggregates and in sepsis-induced myocardial depression." (PMID 36612199, 2022). "In addition, overexpression of calcium release-activated calcium modulator 1 (Orai1) inhibited the growth of the Th17 population in sepsis and reduced mortality and organ damage in septic mice." (PMID 38558800, 2024).
stomach carcinoma (3 papers, 2020 to 2022). "A screen through a cancer genome database together with functional studies revealed several constitutively active Orai1 single-point mutants (Orai1 H134A, Orai1 A137V, Orai1 L138F, and Orai1 M139V) in TM2 that appear in various human cancers, such as colorectal adenocarcinoma or stomach carcinoma." (PMID 33430308, 2021).
thyroid cancer (3 papers, 2021 to 2023). "Recently STIM1 and Orai1 have been shown to be upregulated in thyroid cancer patient tissue samples as well as in thyroid cancer cell lines compared with primary thyroid cells." (PMID 38089882, 2023). "We show that STIM1 and ORAI1 expression is elevated in thyroid cancer cell lines, compared to primary thyroid cells." (PMID 34155535, 2021). "We show here that, especially STIM1, but to some extent also ORAI1, are upregulated in several thyroid cancers cell lines, compared with normal thyroid cells." (PMID 34155535, 2021). "The differential STIM1 and ORAI1 gene expression analysis data clearly showed an upregulation of these genes in most of the thyroid cancer tissues compared to normal thyroid tissues datasets." (PMID 34155535, 2021). "The expression of both STIM1 and ORAI1 genes was significantly upregulated in both the papillary and combined thyroid cancer tissues (Total), compared to tumor adjacent normal thyroid tissues (NT)." (PMID 34155535, 2021). "The expression and function of STIM1 and ORAI1 in thyroid cancer progression and invasion have, however, remained elusive." (PMID 34155535, 2021). "STIM1 and ORAI1 gene expression was evaluated in thyroid tumor tissues (n = 502) versus normal thyroid solid tissues (n = 58) datasets in the TCGA Thyroid Carcinoma cohort." (PMID 34155535, 2021). "The SOCE is decreaed in STIM1 knockdown and Orai1 knockdown thyroid cancer cells." (PMID 38089882, 2023). "Thus, both STIM1 and ORAI1 are important in regulating SOCE in thyroid cancer cells." (PMID 34155535, 2021). "Thus, both STIM1 and ORAI1 are important regulators of thyroid cancer cell invasion." (PMID 34155535, 2021). "Knock-down of STIM1 or ORAI1 attenuated SOCE, reduced invasion, and the expression of promigratory sphingosine 1-phosphate and vascular endothelial growth factor-2 receptors in thyroid cancer ML-1 cells." (PMID 34155535, 2021).
Acanthocytosis (2 papers, 2017 to 2024). "The present study uncovers a novel pathophysiological mechanism in chorea-acanthocytosis, i.e. deranged regulation of ORAI1 and STIM1 expression with subsequent impairment of store operated Ca2+ entry (SOCE)." (PMID 28743945, 2017). "Previous research from our group has demonstrated that lithium significantly enhances ORAI1 and STIM1 transcript and protein levels, along with increasing SOCE in the neurodegenerative disease Chorea-Acanthocytosis." (PMID 38903530, 2024).